TNF (tumor necrosis factor)
Diseases named in the same sentence as TNF in open-access papers (continued):
Sharing a sentence is not in itself a finding about the gene and the disease.
colitis (continued). "In colitic models, exogenous administration of IAP improved the macroscopically and microscopically finding of colonic inflammation through inhibition of LPS-induced production of TNF-α and IL-6 and TLR-4 dependent pathway." (PMID 30558547, 2018). "Previous investigators showed that Bifico treatment significantly reduced the levels of TNFα in the colon of experimental colitis mice." (PMID 29849501, 2018). "Colitis in IL10 KO mice is attributed to the increased production of inflammatory mediators such as TNF and IL1b as well as to a hyper-activated Th1 response." (PMID 29985419, 2018). "TNF-α, IL-6, NF-κβ, and STAT3 turned out to be associated with intestinal inflammation, leading to a predisposition to colorectal cancer associated with colitis." (PMID 30545135, 2018). "EtOH significantly elevated IL-6 mRNA in colonic mucosa, and DSS-induced colitis elevated mRNA for IL-1β, TNFα and IL-6." (PMID 30389960, 2018). "Fargesin also reduced the production and mRNA expression of TNF-α in colonic mucosa of colitis mice." (PMID 29880739, 2018). "Clinical samples from IBD patients showed that some pro-inflammatory cytokines, like TNF-α, are highly correlated with colitis disease activity." (PMID 29921812, 2018). "Mice lacking TPH-2 (neuronally restricted expression) exhibit increased severity of disease accompanied by elevated TNF-α, IL-1β, and IL-6 levels during experimental colitis compared with wild-type mice." (PMID 30177522, 2018). "To investigate changes in pro-inflammatory cytokine levels in a DSS-induced colitis model, we measured IL-1β, IL-6, and TNF-α levels at the mRNA (RT-PCR) and protein (ELISA) levels in the colon." (PMID 29610929, 2018). "Bergenin (50 mg/kg), 5-ASA (100 mg/kg) and rosiglitazone (20 mg/kg) significantly down-regulated the mRNA and protein expressions of IL-6 and TNF-α in colons of mice with DSS-induced colitis." (PMID 29375382, 2017). "The commonly used benzimidazole albendazole not only enhanced anti-TNF induced regulatory macrophage development, but also potentiated the therapeutic effect of an anti-TNF in the T cell transfer model of colitis." (PMID 28961920, 2017). "It is well known that the increased pro‐inflammatory cytokines (TNF-α, IL-1β and IL-6) observed in our model of colitis amplify the inflammatory cascade and result in intestinal tissue damage in patients with UC." (PMID 28270147, 2017). "The observed clinical and histopathological improvement of colitis upon EPO or cibinetide treatment was also associated with reduced levels of nitrite, TNF, IL-1ß, IL-6, IL-12p70, IL-23, IFN-γ and IL-17A in supernatants of colonic organ cultures." (PMID 29026145, 2017). "Albendazole enhances the induction of regulatory macrophages by anti-TNF and potentiates clinical efficacy in murine colitis." (PMID 28961920, 2017). "In IBD, several inflammatory cytokines, such as interleukin-1β (IL-1β), interleukin 6 (IL-6) and TNF-α, mediate the progression of colitis and CAC18–20." (PMID 28701727, 2017). "In IL-10 gene disrupted mice, experimental colitis is also characterized by reduced GHR expression in the liver driven by TNF-α-induced reduction in nuclear SP3." (PMID 28486400, 2017). "Significantly higher levels of mRNAs of pro-inflammatory cytokines, IL-1β, IL-6, IL-17 and TNF-α, were found as early as day 6 in our colitis model than control group, showing ~5.7, ~6.7, ~12.0 and ~3.2 fold increase, respectively." (PMID 28854223, 2017). "TNF-α level decreased by nearly two-fold and three-fold when colitis-induced mice were treated with free Ral or SMA-Ral, respectively." (PMID 28770521, 2017). "Inhibition of CSF-1 suppressed DSS-induced colitis due to diminished immune cell infiltration of T cells and macrophages in colon tissue and reduction of TNFα, IL-1β and IL-6 levels." (PMID 29261815, 2017).
colitis (continued). "Monocytes and macrophages regulate gut inflammation and the majority of tissue infiltrating cells following reactivation of quiescence colitis are M1 macrophage and are the main source of IL-6, IL-1β, and TNF- α." (PMID 28871257, 2017). "Cystatin from the nematode parasite Ascaris lumbricoides reduces inflammation in a mouse model of DSS-induced colitis by increasing the expression of IL-10, TGFβ with simultaneous reduction of IL-6 and TNFα." (PMID 29141050, 2017). "In colonic tumorigenesis, the inflammatory cells contributed to the colitis by generating proinflammatory cytokines, such as IL-1α, IL-2, IL-6, TNF-α, INF-γ." (PMID 29162930, 2017). "Histamine produced by L. reuteri has previously been shown to inhibit pro-inflammatory cytokines such as TNF via H2 receptors and reduce colitis in an animal model." (PMID 28396655, 2017). "For example, interferon-γ is likely a key player in tumor rejection, while evidence suggests that tumor necrosis factor (TNF)-α is of primary importance in the pathogenesis of ipilimumab-induced colitis." (PMID 29230210, 2017). "Here, we extended our previous findings by showing this loss of NRG4 occurs early in a model of acute colitis, and NRG4 levels are negatively correlated with TNF expression." (PMID 28230865, 2017). "We confirmed that reactivation of colitis significantly increased colonic level of pro-inflammatory cytokines IL-6, IL-1β, and TNF- α and decreased level of colonic anti-inflammatory cytokine TGF-β, but IL-10 levels were not affected." (PMID 28871257, 2017). "The intestinal macrophages of WT colitis mice expressed high levels of TNF-α, IL-1β, IL-6 and iNOS mRNA compared with the intestinal macrophages of WT normal mice." (PMID 28733636, 2017). "In our study, TER successfully alleviated acute colitis by suppressing the high-production of TNF-α, IL-1β, and IL-12 in colon explants." (PMID 28553294, 2017). "In a mouse model of colitis-induced carcinogenesis, the blockade of TNF-α led to reduced mucosal injury and in turn to decreased tumor formation." (PMID 29118756, 2017). "The cytokine expression and secretion signatures responsible for the increased inflammation in Winnie and TNFα KO Winnie were investigated to identify any potential molecular mechanisms mediated by TNFα during early onset colitis." (PMID 28796256, 2017). "Inflammation-associated mouse models of colon cancer show that IL-17A-/- mice exhibit milder sign of colitis and tumor growth and reduced levels of the pro-inflammatory cytokines IL-6 and TNF." (PMID 28881611, 2017). "We found an elevated protein expression of inflammatory cytokines including IL-6, IL-23, IL-1β, and TNF-α in the mucosa of colitis mice compared to the control group." (PMID 29375374, 2017). "Expression patterns of three subpopulations from mLNs of WT colitis mice were also compared, the mRNA expression levels of IL-17, TNFα, and IL-1β were also much higher in CD11b+CD169+ macrophages than those in the other two subpopulations." (PMID 28694804, 2017). "In contrast, the intestinal macrophages of p85α+/− colitis mice expressed similar levels of TNF-α, IL-1β, IL-6 and iNOS mRNA compared with intestinal macrophages of p85α+/− normal mice." (PMID 28733636, 2017). "In vivo, albendazole plus anti-TNF combination therapy was superior to monotherapy in a model of colitis, in terms of both induction of regulatory macrophages and improvement of clinical symptoms." (PMID 28961920, 2017). "In a rat model of chemically induced acute and chronic colitis α-MSH reduced pathological weight loss, fecal blood, TNF-α and nitric oxide production in colon tissue and macroscopic colitis lesions." (PMID 28103316, 2017). "Anti-TNF and albendazole combination therapy was further studied in vivo using the T cell transfer model of colitis." (PMID 28961920, 2017).
colitis (continued). "A large amount of evidence indicates that animals subjected to TNBS-induced colitis suffer from diarrhea, weight loss, disorganization of the colon mucosa and sub-mucosa, and significantly increased MDA content, MPO activity, TNF-α and IL-1β." (PMID 28056930, 2017). "In the current study, niacin was found, for the first time, to inhibit TNF-α production in iodoacetamide-induced colitis model." (PMID 28769047, 2017). "TNF-α and IL-1β are the most important cytokines that are present in colon tissues and involved in the pathogenesis of colitis." (PMID 28574825, 2017). "In fact, an increase in cytokines, including the ‘cytokine triumvirate’ of TNF-α, IL-6 and IL-13, has been recently proposed to play a role in the progression of experimental colitis and human IBD." (PMID 28425943, 2017). "Tumor Necrosis Factor is a pro-inflammatory cytokine found in increased concentrations in the gut mucosa of patients with active colitis." (PMID 28469609, 2017). "Increased serum and tissue levels of pro-inflammatory cytokines such as IL-6, IL-1β and TNF-α are characteristic features of colitis and many other chronic inflammatory diseases." (PMID 28634361, 2017). "In contrast, animals receiving anti-TNF plus 4 mg/animal albendazole combination therapy showed significant improvement in the severity of their colitis, both compared with placebo and compared with anti-TNF alone." (PMID 28961920, 2017). "To further confirm the relationship between LPS/TLR4 and TNFα/NOS2 induction, as well as the role of NF-κB signaling in ulcerative colitis and colitis associated tumorigenesis, we used ex vivo experiments." (PMID 28408791, 2017). "Pro-inflammatory lamina propria-derived TNF-α can also exacerbate colitis through CX3CR1+ DCs indicating that this DC subset also plays role in the maintenance of balanced inflammatory and/or standby conditions upon gut homeostasis." (PMID 28458670, 2017). "As such, anti-TNF therapy has been employed in the treatment of colitis and other inflammatory diseases of the bowel with varying degrees of success." (PMID 28469609, 2017). "TNFα has been shown to be critical for the initiation and progression of colitis and CAC carcinogenesis, and blocking TNFα in mice reduced colorectal carcinogenesis with colitis following AOM and DSS treatment." (PMID 29228570, 2017). "PLP treatment ameliorated colitis in IL-10−/− mice due to a reduction in colonic TNFα, IL-6, IFNγ, COX-2 and nitric oxide synthase (iNOS) expression and modulation of the chemotactic lipid S1P." (PMID 28804483, 2017). "Western Blotting analysis further confirmed that TNF-α was increased but IL-4 was decreased in colitis tissues of Adamts18 KO mice when compared to those of WT control." (PMID 28145888, 2017). "In colon tissues of PBS-treated mice with colitis, the mRNA expression levels of TNF-α, IL-1β, IFN-γ, and IL-17 were considerably increased, whereas that of IL-10 was only slightly increased." (PMID 28701721, 2017). "To investigate predictive markers of TNFα-independent UC in a spontaneous and progressive colitis model, we crossed Winnie mice with TNFα KO (commercial line 5540) to create double KO mice (TNFα KO Winnie)." (PMID 28796256, 2017). "Decarine reduced IL-6 and IL-8 production in TNF-α+IL-1β-induced Caco-2 cells, which indicated anti-inflammatory activity on human colon cells and justified the use of Maqian as a remedy for colitis." (PMID 28383530, 2017). "IL-37b-tg mice protect from DSS-induced colitis, characterized by decreasing clinical disease score, histological score, and TNFα and IL-1β production, but increasing IL-10 production in colon tissue." (PMID 28420941, 2017). "The mRNA expressions of IL-1β, IL-6 and TNF-α in the colons of colitis mice significantly increased, and bergenin (20, 50 mg/kg) and 5-ASA (100 mg/kg) showed obvious inhibition." (PMID 29375382, 2017). "For example, roflumilast has been shown to ameliorate not only the clinical score, but also the expression of TNF-α in murine colitis." (PMID 28617319, 2017).
colitis (continued). "More recently, the immunomodulatory effect of these exosomes against TNF-α transcription was demonstrated in vivo in an experimental colitis model." (PMID 28377922, 2017). "Treatment with ghrelin after induction of colitis has inhibited a rise in mucosal IL-1β and TNF-α concentration." (PMID 27598133, 2016). "The IL-1β, -6, -8, -17 and TNF-α protein levels were downregulated significantly in DSS induced colitis mice treated with Grim19 compared with control mice." (PMID 27258062, 2016). "Previous studies have described that the DSS-induced colitis model induced high amounts of Th1 cytokines (TNF-α, IL-1β, IL-6)." (PMID 27965594, 2016). "Co-transfer of either CD4+CD45RBlo or Treg-of-B cells reduced the levels of IFN-γ, tumor necrosis factor (TNF)-α, IL-6, and IL-17 in the MLNs of mice with colitis." (PMID 27581189, 2016). "Real time RT-PCR quantitation confirmed that pro-inflammatory cytokines and chemokines (CCL2, IL-1β, IL-6, IL-23, TNF-α, IL-17A and IL-17F) were elevated in quiescent and active colitis biopsies." (PMID 27271344, 2016). "Administration of ghrelin after induction of colitis led to faster regeneration of the colonic wall and reduction in colonic levels of IL-1β, TNF-α, and myeloperoxidase." (PMID 27598133, 2016). "The DSS colitis model has been characterized by increased serum levels of IL-6, IL-17, and TNFα and elevated levels of IL-4, IL-6, IL-10 and IFNγ have been reported in chronic colitis." (PMID 27177331, 2016). "In animals with colitis, administration of ghrelin for six days resulted in more than a four-fold reduction in IL-1β in colonic mucosa; whereas concentration of TNF-α was reduced twice." (PMID 27598133, 2016). "When normalized against the sub-optimal or least stable genes, colonic TNF-α expression levels had a higher variability in DSS-experimental colitis, which shifted the results from a significant up-regulation to a non-significant up-regulation." (PMID 27244258, 2016). "In our study, the levels of TNF-α, IFN-γ, and IL-1β were remarkably reduced by AaEE in DSS-induced colitis mice, suggesting that the protective effect of AaEE against colonic injury is related to the downregulation of TNF-α, IFN-γ, and IL-1β." (PMID 27635116, 2016). "Increased expression of IL-1β, IL-6 and tumor necrosis factor α (TNF-α) have been demonstrated in colitis rat model." (PMID 27478747, 2016). "In this study, Grim19 inhibited DSS induced colitis progression and weight loss in mice by downregulating the production of STAT3 and proinflammatory cytokines, including TNF-α and IL-6, in colonic inflammation." (PMID 27258062, 2016). "The therapeutic potency of targeting these cytokines have been demonstrated in actual clinical trials with anti-TNF-α antibodies, as well as in in vivo studies where colitis showed attenuation upon DSS stimulation in IFN-γ−/− mice." (PMID 27293323, 2016). "Another interesting finding of our present study is observation concerning the influence of induction of colitis and administration of ghrelin on mucosal concentration of proinflammatory cytokines, IL-1β, and TNF-α." (PMID 27598133, 2016). "Treating these mice with neutralizing antibodies against TNFα and IL-10 ameliorated colitis severity and prolonged survival." (PMID 27997590, 2016). "Fourteen days after induction of colitis, IL-1β and TNF-α concentration in colonic mucosa in rats treated with ghrelin was similar to that observed in animals without induction of colitis." (PMID 27598133, 2016). "Th17 cells infiltrate during colitis in large numbers to produce IL-17, TNF-α and other proinflammatory cytokines." (PMID 26998523, 2016). "Compared with the control, the serum levels of IL-1β, IL-6, IL-10, IFNγ, and TNFα were increased in DSS colitis mice." (PMID 27177331, 2016). "As a consequence, TNF-α induces the β-catenin target gene expressions including PCNA, Cyclin D1 and c-Myc, thus promoting the colitis-associated tumor development." (PMID 26910375, 2016).
colitis (continued). "Previous studies have demonstrated that ITGA4 is hypermethylated in inflamed colon tissue/colitis, and that the treatment of anti-ITGA4 antibodies further aggravate colitis by IL-1β, TNF-α, and IFN-γ recruitment." (PMID 27111221, 2016). "In the case of acute colitis induced by DSS, short-term psychological stress has been shown to increase expression of IFN-γ, IL-6, and TNF-α, resulting in exacerbated colitis." (PMID 27500935, 2016). "TNF-α is well known to play a pivotal role in inflammatory response both in experimental colitis and in human IBDs." (PMID 27158082, 2016). "To better understand the mechanism by which AMT-E ameliorates the DSS-induced colitis, we assessed the colonic production of the inflammatory cytokines TNF-α and IL-1β and the anti-inflammatory cytokine IL-10." (PMID 27527191, 2016). "The murine DSS-induced colitis model exhibits a distinct cytokine profile with elevated levels of TNF-α, IFN-γ, IL-1β, IL-6, and IL-12." (PMID 27293323, 2016). "It protected against colonic inflammation by reducing TNF-α secretion, NF-κB activation, LTB4, and COX-2 expression." (PMID 27635116, 2016). "As expected, TNF-α levels in the active colitis control specimen were elevated, whereas they were lowered in a biopsy from a UC patient in remission upon conventional therapy." (PMID 27152519, 2016). "To examine the effects of MALT1 inhibitors on the cytokine expression in acute DSS colitis model, we measured the levels of IL-1β, IL-6, TNF, IFN-γ, IL-17A and IL-18 in colons of mice following induction of colitis and treatments with MALT1 inhibitors." (PMID 27105502, 2016). "A438079 treatment significantly decreased levels of TNF and IL-1β in colonic tissues of the mice with colitis, in concordance with inhibition of NF-κB and inflammasome pathways in colon tissues." (PMID 26739809, 2016). "The present study in vivo found that sodium propionate inhibited the up-regulation of proinflammatory factors IL-6, IL-1β, and TNF-α mRNA level in the colon of colitis mice." (PMID 27574508, 2016). "In accordance with our previous reports, the mRNA expression of TNF-α was increased in the colon of Itgam−/− mice after DSS induced colitis." (PMID 27188220, 2016). "In the dextrane sodium sulphate (DSS)-induced colitis mouse model showing features of human ulcerative colitis (UC), it has been shown that TNF-α is decreased in the colon due to CS exposure." (PMID 26523550, 2015). "Reports have shown that RELM-β aggravates pathology during DSS-induced colitis, by activating macrophages and by increasing their production of TNF-α." (PMID 26285214, 2015). "This suggests that the method of TNF ablation can affect the microbial community differently but both approaches provided colitis protection." (PMID 25775453, 2015). "In accordance with our data, it was earlier shown that the retinoic acid, which has an immunomodulatory effect, ameliorates the TBNS colitis via inhibition of TNF-α, IL-6, IL-1β secretion and MPO activity in mice." (PMID 25853847, 2015). "To analyze the effect of the hydatid LL on cytokine production in vivo during DSS-induced colitis, we measured the levels of proinflammatory cytokines (TNF-α, IFN-γ) and the immunoregulatory cytokine IL-10 by ELISA in plasma from mice." (PMID 25844068, 2015). "In this study, we evaluated how TNF ablation affects acute colitis, and how colitis correlates with TNF dependent alterations in the microbiota." (PMID 25775453, 2015). "Considering that TNBS instillation in mice induced an intense colon inflammation, we analyzed the local secretion of IL-1β, IL-6 and TNF-α." (PMID 25853847, 2015). "Three of six patients with grade 3 or 4 colitis required additional immunosuppression with anti-TNF-alpha (infliximab), and one patient with increased liver enzymes was treated with mycophenolate mofetil." (PMID 25761109, 2015). "Because colitis in TNFΔARE mice is due to accumulation of TNF, these results indicate the importance of Tpl2 in transducing TNF signals." (PMID 25781948, 2015).